CDH2 (cadherin 2)
Diseases named in the same sentence as CDH2 in open-access papers (continued):
Sharing a sentence is not in itself a finding about the gene and the disease.
myocardial infarction (4 papers, 2020 to 2023). Gross necrosis of the myocardium, as a result of interruption of the blood supply to the area, as in coronary thrombosis. "A Study about myocardial infarction revealed overexpression of CDH2, CDH12, PCDH17, and PCDH18 in myocardial infarction vascular smooth muscle cells compared with controls." (PMID 35480311, 2022). "CDH2 is overexpressed in cardiac, smooth muscle cells after myocardial infarction." (PMID 36959563, 2023). "VCAM-1 supports angiogenesis, EDNRA mediates induction of CDH2 and VEGF by EDN, thereby contributing to tissue restoration after myocardial infarction, while BMPER is known to play an important role in osteogenesis." (PMID 37686058, 2023).
Obesity (4 papers, 2007 to 2025). Accumulation of substantial excess body fat. "We have identified two QTL genes, Adam12 and Cdh2, as causal genetic variants for atherogenic diet-induced obesity." (PMID 17653278, 2007). "Notably, due to the single-gene resolution achieved by our GWA scans, we firmly establish two QTL genes, Adam12 and Cdh2, as causal variants for obesity in inbred mice." (PMID 17653278, 2007). "Since Adam12 and Cdh2 are the only candadiate gene in each of their QTL regions and further supported by the evidence from knockout and/or transgenic mice, we can safely establish these two QTL genes as casual genetic variants for atherogenic diet-induced obesity in natural inbred mouse populations." (PMID 17653278, 2007). "In this study, we respectively constructed specific miRNA-mRNA regulatory networks of obesity-related ccRCC for both VAT and SAT, and 3 RNA pairs (i.e. hsa-miR-182&ATP2B2, hsa-miR-532&CDH2 in VAT; and hsa-miR-425&TFAP2B in SAT) were finally screened out." (PMID 34621242, 2021).
diabetic retinopathy (3 papers, 2017 to 2022). "In this case, CDH1 and CDH2 mRNAs produce calcium-dependent adhesion proteins (E-cadherin and N-cadherin), which play a fundamental role in intercellular adhesion, and abnormal expression of these genes causes various diseases such as DN, diabetic retinopathy, and epithelial-derived solid tumors." (PMID 35363774, 2022).
disc degeneration (3 papers, 2016 to 2023). "We chose to further test the suspected relationship between CDH2 loss and degenerated NP cells and tissue with an in vivo model of disc degeneration in the rat." (PMID 27292569, 2016). "With disc degeneration, NP cells undergo morphologic and phenotypic changes including loss of CDH2 expression and ability to form cell clusters." (PMID 27292569, 2016). "We hypothesized that the terminal gene of miR-369-3p that plays a functional role in disc degeneration might also pass through BMP2 in addition to CDH2." (PMID 36068615, 2022). "When the preliminary information related to disc degeneration in the Genecard database was combined with the target analysis of miR-369-3p, it was found that CDH2 was not included in the database, and the BMP2 gene was the primary target gene obtained by screening." (PMID 36068615, 2022).
Hypertension (3 papers, 2022 to 2025). The presence of chronic increased pressure in the systemic arterial system. "While evaluating the role of these genes in hypertension and HPO terms, we did find that the upregulation of proteins ALDH1A3, ARMT1, and CDH2 can be crucial in the treatment." (PMID 40940770, 2025).
Intellectual disability (3 papers, 2022 to 2025). "For example, de novo heterozygous mutations, both missense and frameshift, in the human N-cadherin (CDH2) gene have been identified in individuals with a syndromic neurodevelopmental disorder characterized by intellectual disability and corpus callosum agenesis or hypoplasia." (PMID 40766181, 2025).
lymphoma (3 papers, 2018 to 2024). A malignant (clonal) proliferation of B- lymphocytes or T- lymphocytes which involves the lymph nodes, bone marrow and/or extranodal sites. "In order to evaluate potential effect of blocking β1 and β7 integrins and cadherin-2 on lymphoma cell adhesion, we treated Ri-1 and U2904 cell lines with representative antibodies being recommended for blocking assays." (PMID 29949925, 2018). "In the current study on the proliferation and metastasis potential of lymphoma, it was seen that CLP36 silencing could evidently suppress the proliferation and the expression levels of VIM and CDH2 in lymphoma cells." (PMID 39735560, 2024). "Altogether, these results show that integrin β1 and cadherin-2 are required for lymphoma-stromal cell interactions and could partially account for the decrease of adhesion under physioxia precisely validated in time-scale in optical tweezers in this study." (PMID 29949925, 2018). "Further, the levels of metastasis-related proteins cadherin 2 (CDH2) and vimentin (VIM) were calculated to evaluate the metastasis potential of lymphoma cells, and it was evident that the knockdown of CLP36 led to the diminished levels of these two proteins in lymphoma cells (P < 0.05)." (PMID 39735560, 2024). "Further, CLP36 silencing repressed the expressions of Cadherin 2 (CDH2) and Vimentin (VIM) yet promoted those of Bax and Caspase 3 in lymphoma cells, concurrent with the reduction on the phosphorylation of PI3K, AKT and CREB, all of which were confirmed to be positively correlated with CLP36." (PMID 39735560, 2024).
mesothelioma (3 papers, 2019 to 2022). A usually malignant and aggressive neoplasm of the mesothelium which is often associated with exposure to asbestos. "Furthermore, lower expression of CDK7, AKT1, PARP1 (p < 0.1), CCND2 (cyclin D2), CDK2, CDK4, BIRC5 (survivin), PCNA and CDH2 (N-cadherin) (p < 0.005) have been shown to result in longer median survival of patients with mesothelioma." (PMID 36304150, 2022). "However, CDH2 was shown to be a favorable prognostic factor in KIRC and a prognostic risk factor in brain lower-grade glioma (LGG) and mesothelioma (MESO)." (PMID 33850477, 2021).
neuroendocrine tumor (3 papers, 2014 to 2022). "Furthermore, expression of neuroendocrine tumor markers was detected in LNCaP cells stably overexpressing N-cadherin (oe-CDH2, with oe-NC as the negative control and Ctrl as the parental LNCaP cells) via lentiviral transduction." (PMID 34512147, 2021).
rhabdomyosarcoma (3 papers, 2005 to 2020). A rare aggressive malignant mesenchymal neoplasm arising from skeletal muscle. "Decrease in CDH2 expression has previously been correlated with poor prognosis in ES, rhabdomyosarcoma, and Wilms’ tumors." (PMID 25008066, 2014).
schizophrenia (3 papers, 2014 to 2024). A major psychotic disorder characterized by abnormalities in the perception or expression of reality. "For instance, we discovered that the genetic variants rs1944294-T in the CDH2 gene and rs11935573-G in the DCHS2 gene were significantly more common in the “schizophrenia” group than in the healthy volunteers’ group (p < 0.05)." (PMID 38699454, 2024). "In the “schizophrenia-female” group, we observed a significantly higher prevalence of the rs6265-T (V66M) variant in the BDNF gene (p = 0.0180, n = 47) and rs1944294-T (L21Stop) in the CDH2 gene (p = 0.0495, n = 47), with a decrease in the corresponding heterozygous variants." (PMID 38699454, 2024). "Parallel and multistep analysis in this research showed that SLC1A1, DRD2, DRD4, BDNF, ESR1, CDH2, GRIN2B, TNFa, GABBR1, and OLIG2 are common genes between schizophrenia and OCD which ESR1, DRD2, GABBR1, TNFa, and CDH2 are the most important individuals." (PMID 31086558, 2018).
serous ovarian cancer (3 papers, 2017 to 2023). "We drew the heatmap plot to classify the up-regulated and down-regulated analyzed genes including integrins, CDH-1, CDH-2, and Wnt5A in different subtypes of serous ovarian cancer and normal ovary." (PMID 33723319, 2021).
Stroke (3 papers, 2016 to 2023). Sudden impairment of blood flow to a part of the brain due to occlusion or rupture of an artery to the brain. "So far, there has been no direct evidence to show the relationship between CDH2 gene and stroke." (PMID 35480311, 2022).
acute leukemia (2 papers, 2022 to 2024). A clonal (malignant) hematopoietic disorder with an acute onset, affecting the bone marrow and the peripheral blood. "However, clinically relevant data on the role of CDH2 in microenvironment-mediated cancer proliferation and therapy resistance in acute leukemia have until now been scarce, as has the means of clinically targeting this via low toxic agents." (PMID 35977468, 2022).
brainstem glioma (2 papers, 2015 to 2023). "A previous study on brainstem glioma showed that higher expression of CDH2 predicts the progression of malignant tumors and tends to predict a shorter survival time of patients." (PMID 25866482, 2015).
developmental delay (2 papers, 2022 to 2024). "Phenotypic analysis of animals with reduced cdh2 expression exhibited abnormal morphological features, such as developmental delay, and blurred distinction between the mesencephalon and rhombencephalon." (PMID 39449741, 2024).
endometrial adenocarcinoma (2 papers, 2012 to 2021). "In this study, the results showed that the expression of miR-543 was negatively correlated with the expression of CDH2 and positively correlated with the expression of CDH1 in endometrial epithelial cells and endometrial adenocarcinoma cells." (PMID 33860034, 2021).
familial Alzheimer disease (2 papers, 2017 to 2022). A degenerative disease of the brain that causes gradual loss of memory, judgment, and the ability to function socially. "CDH2, a classical cadherin playing roles in the development of the nervous system, was found with the pathogenic copy number variations from 261 early-onset familial Alzheimer’s disease and early/mixed-onset pedigree individuals using high-density DNA microarrays." (PMID 28446202, 2017).
Hydrocephalus (2 papers, 2008 to 2024). Hydrocephalus is an active distension of the ventricular system of the brain resulting from inadequate passage of CSF from its point of production within the cerebral ventricles to its point of absorption into the systemic circulation. "This is further supported by the literature highlighting the role of various tight and adherens junctions, especially N-cadherin (CDH2) in maintaining the integrity of the neuroepithelium and glial progenitor cells and hydrocephalus development." (PMID 39118132, 2024).
knee osteoarthritis (2 papers, 2019 to 2021). "The mutation of CDH2 is associated with knee osteoarthritis in children." (PMID 33964893, 2021). "Cadherin-2 (CDH2) gene polymorphisms were reported to be associated with the induction and development of knee osteoarthritis (OA)." (PMID 31288825, 2019).
liver steatosis (2 papers, 2023 to 2025). "The current diagnostics of hepatic steatosis in pediatric subjects based on US and surrogate indexes need additional improvements, and this can be achieved with a future combination of them in novel algorithms accounting for additional protein markers such as CDH2 and FAP." (PMID 39017916, 2025). "CDH2 and FAP combined with other clinical parameters, represent useful tools for accurate diagnosis of fatty liver, emphasizing the importance of integrating novel markers into diagnostic algorithms for MASLD." (PMID 39017916, 2025). "Statistics associated with the figure reveal that the logit model achieved better diagnostic performance for liver steatosis than the components separately, particularly when comparing with the AUC of LDL (p < 0.0008), CDH2 (p < 0.0137) and FAP (0.0119), but not against FLI (p = 0.0845)." (PMID 39017916, 2025).
Miller-Dieker syndrome (2 papers, 2022 to 2024). "The role of CDH2 in the collective migration of the neural crest has been detailed above and these data when combined present a strong argument for the involvement of CDH2 both in the neural and craniofacial aspects of the Miller-Dieker syndrome." (PMID 36213737, 2022).
oligodendroglioma (2 papers, 2016 to 2025). A well-differentiated (WHO grade II), diffusely infiltrating neuroglial tumor, typically located in the cerebral hemispheres. "For instance, CDH1 mutations predominated in oligodendroglioma and GBM, while CDH2 mutations were not reported for oligodendroglioma." (PMID 40679044, 2025).
pterygium (2 papers, 2020 to 2021). A wedge-shaped fibrovascular lesion arising from the bulbar conjunctiva and extending to the cornea. "There are 6 genes that are highly expressed in pterygium, MYC, CDH2, CCNB1, RELN, RB1, and ERBB4." (PMID 33299863, 2020). "We presume that the LINC00472 network might function in pterygium via the FOXM1 PATHWAY, especially through the regulation of CCNB1, MYC, ERBB4, RELN, RB1, and CDH2 in the ceRNA network." (PMID 33299863, 2020).
schwannoma (2 papers, 2013 to 2026). A benign, usually encapsulated slow growing tumor composed of Schwann cells. "Both states, as well as schwannomas, exclusively overexpress α4-integrin (ITGA4, 1.8-fold, p= 0.003), AP2a (TFAP2A, 1.41-fold, p= 0.009) and Ncad (CDH2, 4.5-fold, p=5.42e-4)." (PMID 23354516, 2013).
Sepsis (2 papers, 2022 to 2024). Sepsis is defined as life-threatening organ dysfunction caused by a dysregulated host response to infection. "Phospholamban (Pln), cadherin-2 (Cdh2) and Nprl3 are found to participate in the pathogenesis of sepsis and promote inflammation." (PMID 38601461, 2024). "mmu_circ_0001679 is reported to regulate the expression of Nprl3, and mmu_circ_0001212 similarly regulates Pln, Cdh2 and Nprl3 expression, which were all increased in the sepsis mice." (PMID 38601461, 2024).
anaplastic astrocytoma (1 paper, 2025). "We have shown that the CDH2 gene was most often mutated in anaplastic astrocytoma (grade 3, 4.08%), while amplifications were present in a smaller percentage of diffuse gliomas and GBMs in which deep deletions were also recorded." (PMID 40679044, 2025). "CDH2 was mutated most frequently (4.08%) in anaplastic astrocytoma (grade 3)." (PMID 40679044, 2025).
arteriovenous malformation in (1 paper, 2022). "Recently, several rare heterozygous CDH2 variants encoding extracellular cadherin repeats and the cytosolic region were associated with ARVC, ACOG syndrome, Peters anomaly, and arteriovenous malformation in the brain." (PMID 36111109, 2022).
behavioural disorder (1 paper, 2012). "Furthermore, a locus for the flank sucking behaviour, a compulsive behavioural disorder most often seen in Doberman Pinchers, was recently mapped to the gene cadherin 2 (CDH2) in a genome-wide association study." (PMID 22844513, 2012).
colorectal adenoma (1 paper, 2012). An adenoma that arises from the colon or rectum. "In 17 of the 41 (42%) colorectal adenomas, we detected CDH2 mRNA." (PMID 23029563, 2012). "All 17 of the CDH2 positive colorectal adenomas were also positive for CDH1 mRNA." (PMID 23029563, 2012). "SNAI1 mRNA was expressed in 78% (n = 32/41), TWIST1 mRNA in 41% (n = 17/41) and CDH2 mRNA in 41% (n = 17/41) of the colorectal adenoma tissue, while normal colon mucosa was negative for these transcription factors." (PMID 23029563, 2012). "Even though it was often proposed that N- and E-cadherin have contrary functions in cancer progression, we could not find a significant inverse correlation between CDH1 and CDH2 mRNA expression in colorectal adenomas or carcinomas." (PMID 23029563, 2012).
Compulsive behaviors (1 paper, 2014). Behavior that consists of repetitive acts, characterized by the feeling that one "has to" perform them, while being aware that these acts are not in line with one's overall goal. "Since extreme circling is defined as an OCD our results not only suggest that CDH2 is associated with the behavioral characteristics seen in the BM, but also imply that CDH2 may related to other kinds of obsessive compulsive behaviors found in dog populations." (PMID 25303325, 2014).
endometrioid tumor (1 paper, 2021). A benign, borderline, or malignant epithelial tumor of the female reproductive system characterized by the presence of glands and/or cysts lined by neoplastic cells that resemble endometrial cells. "Reduced expression of CDH1 and KRT18 was significantly associated with high-grade tumors and non-endometrioid tumor histology, while increased expression CTSB, CDH2 and ZEB1 could be observed in serous tumors." (PMID 34936030, 2021).
Insulin resistance (1 paper, 2019). Increased resistance towards insulin, that is, diminished effectiveness of insulin in reducing blood glucose levels. "Cadherin 3, type 1, P-cadherin (CDH3), CDH2, PCDH20, and CDH23 are novel biomarkers for the development of insulin resistance." (PMID 30678306, 2019).
intervertebral disc degeneration (1 paper, 2022). "Recent studies have found that CDH2 is also highly expressed in normal NP cells and is gradually downregulated with the development of intervertebral disc degeneration." (PMID 36068615, 2022).
intracerebral hemorrhage (1 paper, 2020). A cerebrovascular disorder characterized by bleeding into one or both cerebral hemispheres including the basal ganglia and the cerebral cortex. "Focal injection of antibody against cadherin-2 is sufficient to induce intracerebral hemorrhage." (PMID 32687500, 2020).
intracranial meningioma (1 paper, 2021). A meningioma that arises within the cranial cavity. "MSI of CDH2 gene was not statistically significantly associated with a particular grade, but it occurred at relatively similar frequencies across all stages of malignancy contributing to genome instability already in the early stages of intracranial meningioma development." (PMID 33915799, 2021). "The markers for CDH2 gene D18S66 and D18S819 were found to be highly informative with 100% heterozygosity in a total sample of 70 intracranial meningioma." (PMID 33915799, 2021). "Our samples of intracranial meningioma showed that, if the CDH1 gene has a genetic change, it is very likely that the CDH2 gene will also be altered." (PMID 33915799, 2021).
iron deficiency (1 paper, 2020). "The effects of iron deficiency by DFO on the EMT and immune checkpoints were assessed by measuring the mRNA levels of CDH2 and CD274, respectively." (PMID 33302911, 2020).
leiomyosarcoma (1 paper, 2019). An uncommon, aggressive malignant smooth muscle neoplasm, usually occurring in post-menopausal women. "Silencing the SNAI2 gene could significantly upregulate the expression of CDH1, downregulate the expression of vimentin and CDH2 in leiomyosarcoma cells, and significantly impair the proliferation and invasiveness of cells." (PMID 31749661, 2019).
Macrocephaly (1 paper, 2024). Occipitofrontal (head) circumference greater than 97th centile compared to appropriate, age matched, sex-matched normal standards. "From these genes, four are associated either with microcephaly (CUL3 [MIM: 603136]) or macrocephaly (CDH2 [MIM: 114020], GLI3 [MIM: 165240], and WNT5A [MIM: 164975])." (PMID 39168120, 2024).
mesenchymal tumor (1 paper, 2025). "In the third category there were seven studies on epithelial mesenchymal transition (EMT)/TGFb/mesenchymal tumor (EMT/TGFb/Mes) according to the authors, with specific genes CDH1,2, VIM, and TGFb1,2,3 in studies as follows: E16 (CDH1,2, TGFb1, VIM), E24 (TGFb1), E31, E38, E39, E43 (CDH2), and E46." (PMID 40867621, 2025).
myelomeningocele (1 paper, 2020). Myelomeningocele is the most severe form of spina bifida. "CDH2, which codes for a cadherin cell adhesion protein, associated with myelomeningocele in the MA population." (PMID 32970752, 2020). "The genes PORCN, DVL2, CDH2, FUZ are already suspected to play a role in NTD development from studies in animal models and in some cases humans, however the remaining thirteen genes reported here are new in their possible association with myelomeningocele." (PMID 32970752, 2020).
nephritis (1 paper, 2024). Inflammation of renal tissue. "Besides the establishment of the protocol for FFPE sections, we found CDH2 as a marker upregulated in cellular crescents of murine NTS‐nephritis." (PMID 39334561, 2024).